LINC01410 (long independently transcribed non-coding RNA 1410)
Gene: Long non-coding RNA gene on chromosome 9 (62,801,434 to 62,890,983, forward strand). Ensembl gene ENSG00000238113.
Diseases named in the same sentence as LINC01410 in open-access papers:
LINC01410 is named in the same sentence as 20 diseases in open-access papers, as found by Europe PMC text mining. Sharing a sentence is not in itself a finding about the gene and the disease. The quoted sentences say what the papers report.
gastric cancer (6 papers, 2020 to 2022). A primary or metastatic malignant neoplasm involving the stomach. "For instance, LINC01410, as an illustrated sponge of miR-532-5p, promoted the angiogenesis and metastasis of gastric cancer, while miR-532-5p was found to mediate the function of LINC01410 via attenuating the NF-kappaB signaling." (PMID 35896973, 2022). "Recent studies have reported that LINC01410 is overexpressed in several cancers, including colon tumor, gastric cancer, and thyroid carcinoma." (PMID 34322379, 2021). "Previous studies revealed that LINC01410 is an oncogene in cholangiocarcinoma, colon tumor, gastric cancer and thyroid carcinoma." (PMID 33401246, 2020). "It has been shown that LINC01410 overexpression induces gastric cancer metastasis and angiogenesis via NF-κB." (PMID 33401246, 2020). "LINC01410 contributes to angiogenesis and metastasis in gastric cancer via inhibiting the miR‐532‐5p expression." (PMID 32886453, 2020). "Recently, LINC01410 was identified as an oncogene in cholangiocarcinoma, colon tumor, gastric cancer and thyroid carcinoma." (PMID 33401246, 2020). "Notably, LINC01410 is high‐expressed in diverse tumors, including gastric cancer, cervical cancer, and cholangiocarcinoma." (PMID 32886453, 2020). "Likewise, LINC01410 has been elucidated in gastric cancer metastasis and development by miR-532." (PMID 34391433, 2021).
cervical cancer (3 papers, 2020 to 2024). A primary or metastatic malignant neoplasm involving the cervix. "LINC01410 has been reported to be abnormally expressed in cervical cancer and promotes the growth and invasion of cancer cells by regulating the miR-2467/VOPP1 axis." (PMID 35087800, 2021).
cholangiocarcinoma (3 papers, 2020 to 2025). A carcinoma that arises from the intrahepatic biliary tree (intrahepatic cholangiocarcinoma) or from the junction, or adjacent to the junction, of the right and left hepatic ducts (hilar cholangiocarcinoma). "LINC01410 is notably overexpressed in various malignancies, including papillary thyroid carcinoma, endometrial carcinoma, cholangiocarcinoma, neuroblastoma, bladder cancer, gallbladder cancer, cervical carcinoma, and osteosarcoma." (PMID 41472748, 2025). "In conclusion, LINC01410 may serve as an effective therapeutic target in cancers such as cholangiocarcinoma and bladder cancer." (PMID 41472748, 2025). "LINC01410 regulates miR‐124‐3p to increase the SMAD5 expression, elevating cholangiocarcinoma cell proliferation, and migration rates." (PMID 32886453, 2020). "Studies on cholangiocarcinoma (CCA) have demonstrated that LINC01410 acts as a sponge for miR-124-3p, upregulating SMAD5, thereby promoting the proliferation, invasion, and migration of CCA cells and tissues." (PMID 41472748, 2025).
colon tumor (3 papers, 2020 to 2021). "Luo and colleagues indicated that LINC01410 was highly expressed in colon cancer specimens and that knockdown of LINC01410 reduced cell invasion, growth and cell cycle progression." (PMID 33401246, 2020). "Knockdown of LINC01410 attenuates cell growth and arrests cell cycle at G0/G1 phase via suppressing miR‐3128 in colon cancer." (PMID 32886453, 2020). "Furthermore, LINC01410 regulated colon cancer cell invasion, growth and cell cycle progression by sponging miR-3128." (PMID 33401246, 2020).
osteosarcoma (3 papers, 2020 to 2025). A usually aggressive malignant bone-forming mesenchymal neoplasm, predominantly affecting adolescents and young adults. "In osteosarcoma, LINC01410 overexpression is significantly associated with pulmonary metastasis, TNM staging, and poor prognosis." (PMID 41472748, 2025). "Overexpression of LINC01410 induced N-cadherin and vimentin expression while inhibiting E-cadherin expression in osteosarcoma cells." (PMID 36326314, 2022). "We determined that LINC01410 was overexpressed in osteosarcoma specimens and cell lines and that ectopic expression of LINC01410 induced cell invasion and growth by regulating miR-3128 in osteosarcoma." (PMID 33401246, 2020). "The expression of LINC01410 was upregulated in 22 osteosarcoma patients (22/30, 73%) compared to control normal samples." (PMID 33401246, 2020). "We found that LINC01410 was overexpressed in osteosarcoma cells (MG-63, HOS, SAOS-2 and U2OS) compared with osteoblast cells (hFOB1.19)." (PMID 33401246, 2020). "The expression of LINC01410 was upregulated in 22 osteosarcoma patients compared to control normal samples." (PMID 33401246, 2020). "In summary, we determined that LINC01410 was overexpressed in osteosarcoma specimens and cell lines and that ectopic expression of LINC01410 induced cell invasion and growth by regulating miR-3128 in osteosarcoma." (PMID 33401246, 2020). "Overexpression of LINC01410 induced N-cadherin and Vimentin expression and inhibited E-cadherin expression in osteosarcoma cells." (PMID 33401246, 2020). "Ectopic expression of LINC01410 promoted the osteosarcoma cell cycle, proliferation and invasion." (PMID 33401246, 2020). "In our study, LINC01410 was overexpressed in osteosarcoma specimens and cell lines." (PMID 33401246, 2020). "The LINC01410 level was higher in osteosarcoma specimens than in control normal samples." (PMID 33401246, 2020). "Moreover, LINC01410 overexpression increased osteosarcoma cell invasion and growth by modulating miR-3128." (PMID 33401246, 2020). "To explore whether LINC01410 plays an oncogenic role in osteosarcoma by regulating miR-3128, we transfected LINC01410-overexpressing MG-63 cells with a miR-3128 mimic." (PMID 33401246, 2020). "We determined that LINC01410 was overexpressed in osteosarcoma specimens and cell lines." (PMID 33401246, 2020). "Furthermore, LINC01410 overexpression increased osteosarcoma cell invasion and growth by modulating miR-3128." (PMID 33401246, 2020). "However, the role of LINC01410 in osteosarcoma has not been verified." (PMID 33401246, 2020).
thyroid carcinoma (3 papers, 2020 to 2021). "For instances, LINC01410 silencing retards cell proliferation and facilitates apoptosis via regulating miR‐3619‐5p/FOXM1 axis in thyroid carcinoma." (PMID 32886453, 2020).
bladder cancer (2 papers, 2021 to 2025). "In studies related to bladder cancer (BC), it has been confirmed that LINC01410 functions as a sponge for miR-4319, upregulating Snail1, thereby promoting the proliferation, migration, invasion, and epithelial-to-mesenchymal transition (EMT) of BC cells." (PMID 41472748, 2025). "The role of LINC01410 in bladder cancer cells progression through miR-4319/Snail1 axis was explored by CCK-8 assay." (PMID 34391433, 2021). "Results of TCGA database indicated a high expression of LINC01410 in bladder cancer (BC) development." (PMID 34391433, 2021). "Furthermore, qRT-PCR analysis showed expression levels of LINC01410 in non-metastasis samples (n = 28) and metastasis samples (n = 32) exhibited a significantly higher expression of LINC01410 in the tissues with metastasis of bladder cancer (P < 0.001)." (PMID 34391433, 2021).
neuroblastoma (2 papers, 2020 to 2025). Neuroblastoma (NB) is the most common solid, extracranial childhood tumor. "LINC01410 is implicated in the glycolytic pathway, with aberrant expression influencing the progression of esophageal cancer and neuroblastoma." (PMID 41472748, 2025). "In neuroblastoma, LINC01410 enhances the expression of WEE1 by acting as a sponge for miR-506-3p, thereby promoting the progression of the cell cycle." (PMID 41472748, 2025).
atherosclerosis (1 paper, 2019). A disease characterized by the build-up of fatty material and calcium deposition in the arterial wall resulting in partial or complete occlusion of the arterial lumen. "Of note, we observed lncRNAs in module 5, such as RP11-171N4.1, DKFZP434K028, LOC101929153, LGALS8-AS1, and LINC01410, were significantly involved in regulating immune system responses and inflammation responses, which had been reported to be key regulators in atherosclerosis." (PMID 30873207, 2019).
diabetic nephropathy (1 paper, 2025). "LINC01410 also plays a critical regulatory role in the pathogenesis and progression of certain non-malignant diseases, such as preeclampsia and diabetic nephropathy." (PMID 41472748, 2025). "Intriguingly, LINC01410 exhibits opposite expression patterns in non-malignant conditions such as preeclampsia and diabetic nephropathy, highlighting its context-dependent biological function." (PMID 41472748, 2025).
esophageal cancer (1 paper, 2025). A primary or metastatic malignant neoplasm involving the esophagus. "In esophageal cancer, LINC01410 acts as a ceRNA by sponging miR-122-5p, thereby upregulating PKM2, respectively, ultimately contributing to the progression." (PMID 41472748, 2025). "For instance, exosome-derived LINC01410 has been shown to promote the progression of esophageal cancer." (PMID 41472748, 2025). "In esophageal cancer research, experiments have shown that LINC01410 indirectly upregulates the expression of PKM2 in ESCC cells and tissues by acting as a sponge for miR-122-5p, thereby promoting ESCC cells migration, invasion, and EMT." (PMID 41472748, 2025). "In research focused on esophageal cancer, experimental findings revealed that exosome-derived LINC01410 acts as a molecular sponge for miR-122-5p, thereby indirectly promoting the upregulation of PKM2 in esophageal cancer cells." (PMID 41472748, 2025).
glioblastoma (1 paper, 2025). The most malignant astrocytic tumor (WHO grade IV). "Additionally, in glioblastoma, the overexpression of LINC01410 is linked to tumor size and WHO grading." (PMID 41472748, 2025). "In glioblastoma, high LINC01410 expression has been shown to correlate with malignant progression; its knockdown promotes apoptosis, enhances PTEN expression, and suppresses AKT phosphorylation." (PMID 41472748, 2025). "In glioblastoma, LINC01410 acts as a sponge for miR-506-3p, thereby promoting NOTCH2 expression and activating the Notch pathway, which stimulates GBM cell proliferation and inhibits apoptosis." (PMID 41472748, 2025).
glioma (1 paper, 2025). A benign or malignant brain and spinal cord tumor that arises from glial cells (astrocytes, oligodendrocytes, ependymal cells). "In glioma, studies have shown that the deletion of LINC01410 results in a marked reduction in the expression of Cyclin D1, CDK6, and Bcl-2, while simultaneously elevating the expression of Bax." (PMID 41472748, 2025).
non-small cell lung carcinoma (1 paper, 2025). A group of at least three distinct histological types of lung cancer, including non-small cell squamous cell carcinoma, adenocarcinoma, and large cell carcinoma. "In addition to its remarkable clinical diagnostic and prognostic value in non-small cell lung cancer, circulating LINC01410 has also been reported to be upregulated in both colorectal cancer tissues and cell lines." (PMID 41472748, 2025).
cancer (4 papers, 2020 to 2025). A tumor composed of atypical neoplastic, often pleomorphic cells that invade other tissues. "The altered expression of LINC01410 is closely associated with various clinicopathological characteristics and poor prognosis in cancer." (PMID 41472748, 2025). "LINC01410 has been shown to regulate four distinct signaling pathways, thereby promoting the initiation and progression of cancer." (PMID 41472748, 2025). "Exosome-derived LINC01410 modulates gene expression in recipient cells, playing a pivotal role in cancer development." (PMID 41472748, 2025). "LINC01410 is engaged in the regulation of multiple protein levels and exerts a crucial influence in the progression of cancer." (PMID 41472748, 2025). "LINC01410 is involved in the regulation of four distinct signaling pathways that influence cancer progression." (PMID 41472748, 2025). "Therefore, both LINC01410 and cancer-related proteins present considerable potential as biomarkers and therapeutic targets in cancer treatment, offering profound clinical significance." (PMID 41472748, 2025). "LINC01410 is upregulated in 15 types of cancer and inhibits the expression of 12 distinct miRNAs." (PMID 41472748, 2025). "LINC01410 has been proved to exhibit carcinogenic function in cancers." (PMID 32886453, 2020). "This review highlights the latest discoveries regarding the roles of LINC01410 in human cancers and certain non-malignant diseases." (PMID 41472748, 2025).
tumor (4 papers, 2020 to 2025). "Beyond its aberrant expression in tumor tissues, emerging evidence highlights the diagnostic and prognostic potential of circulating LINC01410 in peripheral blood." (PMID 41472748, 2025). "Consequently, LINC01410 overexpression is closely associated with critical clinicopathological features, including tumor size, invasion depth, lymph node metastasis, and TNM staging." (PMID 41472748, 2025). "The results reveal that LINC01410 is significantly overexpressed in ESCC tumor tissues compared to adjacent normal tissues." (PMID 41472748, 2025). "In summary, LINC01410 indirectly regulates key enzymes involved in glycolysis, thereby promoting tumor cell proliferation." (PMID 41472748, 2025). "Whereas, inhibitory effects of miR-4319 mimics on BC cell growth and invasiveness were maintained by LINC01410 upregulation, and the tumor suppressor effect of miR-4319 was consistent with that of other studies." (PMID 34391433, 2021). "Lastly, suppression of miR-4319 markedly abolished the repressive effects of knocking down of LINC01410 on proliferation and invasion of BC cells, confirming that it was a tumor suppressor in BC." (PMID 34391433, 2021). "Further experiments also showed that overexpression of LINC01410 also induced a significant acceleration in the tumor growth in vivo, together with increased rate of metastasis to distant organs." (PMID 34322379, 2021). "Data from tumor growth curves and histograms demonstrated significantly reduced tumor size and mass in the mice inoculated with LINC01410 knockouts in comparison to control groups with statistical significance of P < 0.05." (PMID 34391433, 2021). "The LINC01410 expression in tumor tissues was markedly increased compared with the adjacent tissues in NBL patients (P < .001)." (PMID 32886453, 2020). "LINC01410 was significantly upregulated in the GBC tissues compared to adjacent non-tumor tissues." (PMID 34322379, 2021). "In vivo, LINC01410 knockdown could markedly reduce the tumor volume at 3 and 4 weeks after inoculation (P < .01), as well as reduce the tumor weight (P < .01)." (PMID 32886453, 2020). "Similarly, LINC01410 knockdown alleviated the tumor growth in mice, indicating the important function of silencing LINC01410 in suppressing NBL tumorigenesis in vivo." (PMID 32886453, 2020). "Consequently, the downregulation of LINC01410 expression in tumor cells may effectively hinder the progression of glycolysis and slow tumor cell proliferation, whereas elevated LINC01410 expression can significantly contribute to the improvement of DN." (PMID 41472748, 2025). "LINC01410 promotes oncogenesis by modulating key signaling pathways, such as PTEN/AKT, Notch, ErbB, and NF-κB, interacting with non-coding RNA networks, and influencing the expression of proteins involved in tumor biology." (PMID 41472748, 2025). "It is noteworthy that the long non-coding RNA LINC01410 binds to miR-532-5p through a molecular sponge mechanism, thereby relieving its inhibition of FASN, ultimately accelerating LD accumulation and fatty acid metabolic reprogramming, and promoting EMT, invasion, and LNM of tumor cells." (PMID 41472748, 2025). "Furthermore, we detected LINC01410 expression in 96 pairs of GBC samples and adjacent non-tumor tissues using qRT-PCR and found that LINC01410 was more highly expressed in CRC tissues than in the paired non-tumor tissues, and LINC01410 was over-expressed more than 2.0 fold in 82.3% of GBC samples." (PMID 34322379, 2021).
LINC01410 also shares sentences with these, for which no sentence is quoted: colon cancer (2 papers); hepatocellular carcinoma (1); preeclampsia (1); thyroid tumor (1).